RNU6-560P (RNA, U6 small nuclear 560, pseudogene)
Gene: Small nuclear RNA gene on chromosome 11 (86,153,227 to 86,153,334, forward strand). Ensembl gene ENSG00000200877.
Homologues: Orthologues: chimpanzee U6 (99% identical), pig U6 (82% identical), dog U6 (76% identical), mouse Gm26279 (72% identical). Paralogues in human: RNU6-28P (91% identical), RNU6-774P (91% identical), RNU6-86P (91% identical), RNU6-11P (90% identical), RNU6-1209P (90% identical), RNU6-222P (90% identical), RNU6-37P (90% identical), RNU6-1309P (89% identical), RNU6-1316P (89% identical), RNU6-21P (89% identical), RNU6-1 (88% identical), RNU6-1175P (88% identical), and 1288 more.